INS (insulin)
Diseases named in the same sentence as INS in open-access papers (continued):
Sharing a sentence is not in itself a finding about the gene and the disease.
Insulin resistance (continued). "In Zucker fatty rats, BT2 rapidly lowers hepatic triglycerides and improves glucose tolerance and insulin sensitivity, and treatment of ob/ob and diet‐induced obese mice with BT2 restores BCAA catabolism and is sufficient to improve glucose tolerance and insulin resistance." (PMID 35526271, 2022). "Insulin treatment reduced the insulin resistance in APOE4 carriers but not in APOE4-negative ones." (PMID 36547082, 2022). "Another probable hereditary reason for insulin resistance in PCOS is a significant rate of SH2 domain-containing adaptor protein (Lnk) activity in PCOS female's ovarian cell lines, which suppresses the MAPK-ERK and phosphatidylinositol 3-kinase-AKT signaling responses to insulin." (PMID 35356614, 2022). "Serum total cholesterol, high-density lipoprotein cholesterol (HDL-C), and low-density lipoprotein cholesterol (LDL-C) increased significantly, while intriguingly, there were no alterations in serum glucose, insulin, or the Homoeostatic Model Assessment for Insulin Resistance (HOMA-IR) scores." (PMID 35894647, 2022). "With insulin resistance, cells of the body do not respond normally to insulin." (PMID 35565811, 2022). "The OM3-diet also stabilized glucose levels and insulin homeostasis, as measured by the Calculated Homeostasis Model Assessment for Insulin Resistance (HOMA-IR) and levels of adiponectin, a hormone produced by the adipose tissue that alleviates insulin resistance." (PMID 36293015, 2022). "Among 25 participants with insulin resistance and metabolic syndrome, fenofibrate reduced plasma TG as well as inflammatory markers interleukin-6 (IL-6) and high-sensitivity C-reactive protein (hsCRP), but did not improve insulin sensitivity." (PMID 35457120, 2022). "We examined the degree of insulin resistance that could affect the expression of the mRNA panel, so, we divided the group with T2DM into two subgroups, one with insulin resistance (HOMA-IR ≥ 2.5) and the other subgroup being insulin sensitive (HOMA-IR < 2.5)." (PMID 36139069, 2022). "Previous studies have suggested leptin might help in the increased insulin sensitivity as well as improved insulin resistance while such benefits are absent in diabetic patients with obesity due to leptin resistance." (PMID 34996484, 2022). "Unfortunately, HOMA-IR is the least accurate, partly because of the lack of standardization of insulin immunoassays, which may have led to inconsistent conclusions in previous studies analyzing the relationship between osteocalcin and insulin resistance." (PMID 36601005, 2022). "At variance, endocrine transfer could lead to lipid storage in muscle and insulin non-target cells (e.g., endothelial and blood) and thereby contribute to the development of insulin resistance and diabetic late complications, respectively." (PMID 35806423, 2022). "We examined insulin and leptin signaling pathways in the hippocampus and cortex to assess whether GMT ameliorated brain insulin resistance and leptin resistance, given that these pathways play key roles in maintaining blood glucose homeostasis and brain function." (PMID 35721013, 2022). "Results showed that maternal LP diet during puberty and adulthood did not alter the insulin sensitivity and hepatic lipid homeostasis of their offspring under chow diet, but aggravated insulin resistance, hepatic steatosis, and hypercholesterolemia of offspring in response to a post-weaning HFD." (PMID 36235710, 2022). "Thus, it can reduce fasting blood glucose and insulin resistance and reduce inflammation by decreasing serum levels of IL-6, TNF-α, and resistin and increasing serum levels of adiponectin and irisin, which ultimately improve insulin sensitivity." (PMID 36355818, 2022). "In previous studies, we could show that valvular interstitial cells (VIC) display canonical elements of classical insulin signaling and develop insulin resistance upon hyperinsulinemia and hyperglycemia accompanied by impaired glucose metabolism." (PMID 36386326, 2022).
Insulin resistance (continued). "A novel non–insulin-based metabolic score for insulin resistance (METS‐IR) index has been proposed as a simple and reliable alternative insulin resistance (IR) marker, but its the predictive value in asymptomatic adults with coronary artery calcification (CAC) remains unclear." (PMID 36357872, 2022). "In addition, as recently reported, high molecular weight adiponectin is positively associated with insulin secretion (evaluated using HOMA-β%), with or without the adjustment for insulin resistance." (PMID 36295825, 2022). "Although the adipose tissue does not secrete insulin, adiposity contributes to insulin resistance and might explain the mediated effect through plasma." (PMID 36407523, 2022). "However, Asians do not develop hyperinsulinemia when insulin resistance occurs because of the small pancreatic β-cell mass and low insulin secretion capacity." (PMID 35054379, 2022). "Hypersecretion of insulin during a glucose tolerance test, independent of insulin resistance or blood glucose levels, may serve as an early predictor of those at risk for developing type II DM." (PMID 36278750, 2022). "In summary, the telmisartan-rosuvastatin treatment combination did not significantly improve insulin resistance, but preserved insulin secretion, improved fasting blood glucose, and reduced the risk of NODM more than the amlodipine-rosuvastatin combination in hypertensive ASCVD patients with IFG." (PMID 36086748, 2022). "As abdominal obesity and insulin resistance progress, the pulsatility of insulin release decreases, leading to defective insulin signaling in hepatocytes, including CEACAM1 phosphorylation and, subsequently, reduction in hepatic insulin clearance to contribute to chronic hyperinsulinemia." (PMID 36009446, 2022). "However, a closer look indicated that starch consumption was not related to insulin resistance, and fiber intake fits hand-in-hand with increased insulin sensitivity." (PMID 35267895, 2022). "It is also clear that whilst exercise may protect against some aspects of insulin resistance, it is unable to prevent its remorseless progression to T2DM in those who continue to eat diets that produce persistently raised blood insulin concentrations (hyperinsulinemia) over many decades." (PMID 35215511, 2022). "It is noteworthy that recent work demonstrated that the increase in insulin secretion in obese subjects occurs even in the absence of insulin resistance, thus representing an early abnormality that precedes and contributes to the development of insulin resistance." (PMID 35628332, 2022). "It is also found that there are significantly higher kisspeptin levels in normal-weight PCOS subjects than in obese women with the disease with a negative relation to BMI, androgens, fasting insulin levels, and Homeostatic Model Assessment for Insulin Resistance (HOMA-IR)." (PMID 36407241, 2022). "Finally, the lack of fasting insulin in this study makes it difficult to analyze information on insulin resistance." (PMID 35405947, 2022). "The combined results demonstrate that CM supplementation improved the efficacy of (or sensitivity to) insulin, likely by improving insulin effectiveness and/or uptake independent of changes to β-cell function (i.e., improved insulin sensitivity and decreased insulin resistance)." (PMID 35804599, 2022). "Studies have explored the impact of MSTN on insulin resistance, and several studies conducted using mouse models have provided evidence that the absence of MSTN has significant effects on metabolism, that is, it improves insulin sensitivity and reduces obesity." (PMID 35812316, 2022). "The fact that the insulin sensitivity was not altered suggests that vascular insulin resistance may be an early event that happens before whole-body insulin resistance." (PMID 35676248, 2022). "Insulin resistance: a condition whereby cells do not respond properly to insulin." (PMID 35319749, 2022).
Insulin resistance (continued). "Furthermore, a lack of RAC1 is associated with insulin resistance in humans and rodents and ELMO2 and RAC1, both regulate the insulin dependent membrane translocation of the glucose transporter 4 (GLUT4) in muscle cells." (PMID 35874819, 2022). "We conclude with the perspective that the commonly observed lower insulin clearance rate in people with obesity, compared with lean people, is not a compensatory response to insulin resistance but occurs because insulin sensitivity and insulin clearance are mechanistically, directly linked." (PMID 35054781, 2022). "Thus, genes in the insulin signalling pathway, such as the insulin receptor (INSR), insulin receptor substrates 1 and 2 (IRS1 and IRS2), and GLUT4, are attractive candidates for insulin resistance." (PMID 35627115, 2022). "However, fasting glucose and insulin concentrations and the homeostatic model assessment index as a measure of insulin resistance did not change." (PMID 36030401, 2022). "Even though insulin resistance was not directly assessed in the current study, it is likely that subjects with increasing levels of glucose intolerance are more insulin resistant than those with NGT and, accordingly, have increasing concentrations of plasma mannose." (PMID 36151569, 2022). "When the mechanisms of insulin function are considered to be quantitative or continuous variables from an evolutionary perspective, it is likely that all women with PCOS, whether obese or lean, have insulin resistance." (PMID 35456928, 2022). "The levels of triglyceride, glucose, insulin, C-reactionprotein (CRP), TNF-α, and total antioxidant capacity (T-AOC) in plasma were increased in OH rats, which were markedly decreased by ADM application in HFD-fed rats, as well as HOMA-IR (homeostasis model assessment of insulin resistance)." (PMID 35745637, 2022). "One study in normal settings showed that p66Shc has a positive role in insulin pathway through its ROS dependent activity, but this study was not accounted for context of nutrient overload and insulin resistance, and it is possible that p66Shc induces insulin response in normal settings." (PMID 36465704, 2022). "Furthermore, orlistat selectively reduces visceral fat and prevents the digestion of free fatty acids, which are responsible for the increase in hepatic and peripheral insulin resistance, and increases the secretion of two gut hormones, GLP-1 and GIP, thus improving insulin release." (PMID 36432488, 2022). "When it comes to specific endocrine and metabolic evaluations, the homeostasis model assessment of insulin resistance (HOMA-IR), fasting insulin level, glucose/insulin ratio, and quantitative insulin sensitivity check index (QUICKI) may be used to confirm the presence of IR." (PMID 36292208, 2022). "However, the effect of CRP on other key nodes in the insulin signaling pathway such as the IR have not been researched to fully elucidate its role in insulin resistance." (PMID 35883605, 2022). "Subgroup analysis 1: effect of adiposity on insulin kinetics, independent of insulin resistance." (PMID 34905513, 2022). "However, since the beta cells were artificially destroyed by STZ leading to basal levels of plasma insulin in DD/STZ mice, the HOMA-IR (which is determined by fasting glucose and insulin levels) would not be accurate in showing insulin resistance in mice." (PMID 35784349, 2022). "The continuity of a HFD in diabetic rats may imply that the insulin resistance installed by the HF diet was not compensated by additional insulin secretion." (PMID 35163209, 2022). "Plasma GRP78 levels in insulin resistance patients are higher than in healthy people and those who returned to normal physiology after duodenal jejunal bypass surgery, and plasma GRP78 level was negatively correlated with insulin sensitivity but positively correlated with body mass index (BMI)." (PMID 36498048, 2022).
Insulin resistance (continued). "Given that ε4 negative AD patients had previously shown signs of insulin resistance, this study suggested that cognitive effects in response to intranasal insulin may indicate disrupted insulin metabolism in AD and MCI patients that do not carry the ε4 allele." (PMID 36429060, 2022). "Obesity leads to ectopic fat deposition and lack of insulin signal transduction, triggers insulin resistance, inhibits liver glycogen synthesis, and increases liver gluconeogenesis, especially in peripheral tissues such as fat cells, leading to abnormal lipid metabolism." (PMID 35242879, 2022). "Second, the levels of insulin resistance or insulin secretion were not assessed, and thus, some participants without common major metabolic abnormalities but with isolated insulin resistance may have been overlooked." (PMID 36501152, 2022). "Similar to our previous finding, we also found DEX-induced impairments of insulin resistance and sensitivity, assessed by HOMA-IR and Matsuda index, respectively, which are associated with elevations in plasma concentrations of insulin, but not glucose, both at fasting and post-prandial states." (PMID 36077132, 2022). "Paradoxically, hyperactivation of mTORC1 in TSC1-knockout liver and reduced activation of the mTORC1/S6K axis were reported to be protective against diet-induced hepatic steatosis and hepatic insulin resistance, respectively, suggesting negative feedback from mTORC1 on insulin signaling." (PMID 34855620, 2022). "In conclusion, although the number of patients was very small, these results suggested that DPP4i treatment might improve insulin resistance without changing insulin secretion." (PMID 35672759, 2022). "Clinical trials assessing the impacts of curcumin on insulin resistance showed a decrease in circulating GSK-3β and IAPP levels over 12 weeks; this demonstrated a positive effect of glycemic control through a decrease in insulin-resistance fasting serum insulin." (PMID 35408920, 2022). "The increase in GSIS associated with obesity, in conjunction with a decrease in the ICR, can sufficiently increase the basal and postprandial plasma insulin concentrations needed to maintain normoglycemia in individuals with moderate, but not severe, insulin resistance." (PMID 34905513, 2022). "However, there is not a CSF to serum insulin threshold specifically defining CNS insulin resistance, as is the case for HOMA-IR." (PMID 35884888, 2022). "Although the number of patients was very small, these results suggested that DPP4i treatment might improve insulin resistance without changing insulin secretion." (PMID 35672759, 2022). "Thus, vitamin D might have a pivotal role in improving insulin resistance in T2DM patients and raising the sensitivity of peripheral insulin in patients with impaired glucose tolerance." (PMID 36193546, 2022). "In addition, browning has been demonstrated to be independent of insulin signaling; therefore, proving the therapeutic potential of increasing energy expenditure and improving glucose homeostasis during insulin resistance." (PMID 35563150, 2022). "Further, subchronic sleep restriction may increase peripheral insulin resistance without affecting hepatic insulin sensitivity, while sleep extension may improve fasting insulin sensitivity." (PMID 35757614, 2022). "In 3T3-L1 insulin-resistant adipocytes, red CM fruit extract increased ISGU (p = 0.002) compared to IR cells, which might suggest that red CM fruit extract might have reversed the previously developed insulin resistance." (PMID 35684107, 2022). "However, many people with obesity and insulin resistance have normal fasting plasma glucose (NFG) concentrations and normal glucose tolerance (NGT) because of an increase in the plasma insulin concentration that compensates for the defect in insulin action." (PMID 34905513, 2022).
Insulin resistance (continued). "Importantly, we found that in the presence of CA, the palmitate-induced insulin resistance was prevented, and the insulin-stimulated glucose uptake and GLUT4 plasma membrane levels were restored to levels comparable to the response seen with insulin alone." (PMID 35011728, 2022). "However, since not all obese individuals are insulin resistant, fat mass per se, can’t be the sole determinant of insulin resistance." (PMID 35390031, 2022). "Prior studies have demonstrated that low-dose GH may have beneficial effects on insulin resistance and glucose homeostasis due to increased circulating IGF-1, while long-term GH treatment in high doses impairs insulin sensitivity and exacerbates insulin resistance." (PMID 36619543, 2022). "However, as the IUGR F1 rats aged, they had significantly reduced insulin secretion of β-cells (by half the control at 1 week of age and completely absent at 26 weeks of age), insulin-resistance and glucose-intolerance hence hyperglycemia." (PMID 35432208, 2022). "In fact, while in mice the activation of BAT and the promotion of WAT browning ameliorate insulin sensitivity, liver steatosis and glucose tolerance in obesogenic conditions, the impact of WAT browning on obesity or insulin resistance in humans is less relevant." (PMID 36187779, 2022). "The diabetic control group exhibited pancreatic dysfunction as evidenced by the reduction in serum insulin, homeostasis model assessment of ß-cell function (HOMA-β), expressions of PI3K/AKT, Bcl-2, and PCNA combined with an elevation in homeostatic model assessment of insulin resistance (HOMA-IR)." (PMID 35308202, 2022). "Recent evidence suggests that the factors for suppressing insulin signaling can be transmitted between cells via extracellular vesicles (EVs), thereby changing the definition of insulin resistance from a noncommunicable preclinical health condition to a transmissible pathological status." (PMID 36699697, 2022). "Thus, such a class of partial insulin mimickers is probably not beneficial for alleviating insulin resistance." (PMID 35956295, 2022). "There are studies showing that insulin resistance development is a consequence of the elevated concentration of ceramide in the cell, which may influence the insulin signaling pathway by distinct mechanisms that are not entirely clear." (PMID 34204938, 2021). "In agreement with previously published data, we found the increased NFKB1 mRNA level in hyperglycemic and insulin resistant patients with GDM, suggesting that this change may be related to the pathophysiology of hyperglycemia and insulin resistance that are evident in women with GDM." (PMID 33520443, 2021). "A study including 183 individuals (127 individuals without insulin resistance and 56 with insulin resistance) indicated that trans fat intake impairs insulin sensitivity affecting insulin signaling via intracellular kinases, which alters insulin receptor substrates." (PMID 34681504, 2021). "However, differently from males, the lack of nuclear ERα alters the central control of insulin sensitivity in females, which display hyperinsulinemia and insulin resistance due to unrestrained hepatic GNG." (PMID 34572151, 2021). "Therefore, we decided to evaluate the expression of GLUT4 and IRAP markers as well as insulin mRNA in animals that do not express NLRP3 inflammasomes to assess the contribution of neuroinflammation to the development of insulin resistance." (PMID 34769018, 2021). "Although we did not capture fasting plasma insulin, we used other parameters that might serve as a proxy for recognizing insulin resistance." (PMID 33958606, 2021). "Moreover, another study showed that acetate activated the parasympathetic nervous system resulting in increased ghrelin secretion and glucose-stimulated insulin secretion (GSIS), which in turn generated ectopic lipid deposition and insulin resistance in the liver." (PMID 34660662, 2021).